KRAS (KRas proto-oncogene, GTPase)
Diseases named in the same sentence as KRAS in open-access papers (continued):
Sharing a sentence is not in itself a finding about the gene and the disease.
tumor (continued). "Mutant KRAS directly activates downstream signaling pathways like RAF/MEK/ERK and PI3K/AKT, even under normoxic conditions within the tumor microenvironment." (PMID 39273409, 2024). "In view that trametinib treatment downregulates Id1 expression, we analyzed the effects of this treatment on Id1 expression and tumor growth in CMT167 and LLC KRAS-mutant LUAD syngeneic tumors." (PMID 38643157, 2024). "High-level activation of oncogenes (e.g., KRAS, BRAF, and c-MYC) triggers intrinsic tumor suppression 46,50–53." (PMID 36778401, 2024). "After applying miR3655 OE AAV in KRAS G12D MUT xenografted tumors, the growth rate, weight, and volume of the tumor were significantly reduced." (PMID 39523457, 2024). "MiR-21 activates KRAS signaling via the transcription factor ELK1, promoting tumor cell proliferation, migration, and invasion." (PMID 39839479, 2024). "Preclinical findings presented at the AACR 2023 annual meeting indicated that RMC-9805 monotherapy induced tumor regressions in the majority of preclinical PDAC and NSCLC cancer models harboring KRAS G12D." (PMID 39164274, 2024). "A correlation between KRAS and CTLA-4 mRNA expression in CTCs and primary tumor tissues was observed, suggesting a potential role of CTLA-4 in KRAS-mediated CRC progression." (PMID 39539964, 2024). "Among the 10 selected features, tumors with high KRAS VAF exhibited lower 10th percentile values on the Ve map, indicating a tendency towards decreased signal intensity of the tumor." (PMID 38525415, 2024). "The copy numbers of shared CNVs, such as PDGFRA/KIT, CDK4, MYC, KRAS, and VEGFR2, were highly consistent (Pearson correlation = 0.95, P = 0) between the CSF and tumor tissues." (PMID 38388726, 2024). "This is explained by the fact that secondary signal transducers correlated to tumor suppressors (such as SIRT1) or potential oncogens (for example, mTOR, and KRAS) behave pleiotropically depending on the tissue or cell type." (PMID 39203892, 2024). "In KRAS-mutant SUIT-2 cells, FTH1 knockdown led to significant decreases in cancer cell viability via G2/M cell cycle arrest in vitro as well as tumor growth suppression in the SUIT-2 xenograft model in vivo." (PMID 39294443, 2024). "In vivo experiments utilizing H358 tumor xenografts, LLC, and KRAS mutant NSCLC models indicated apigenin treatment effectively inhibited tumor growth." (PMID 39690423, 2024).
tumor (continued). "The KRAS G12C mutation disrupts the normal balance between GDP and GTP binding, reduces the binding of KRAS to GTPase-activating proteins (GAPs), and leads to an overactivation of KRAS in its GTP-bound state, ultimately promoting tumor initiation and growth." (PMID 39433508, 2024). "One study on IGF-1R expression in NSCLC found that treatment with IGF-1R TKIs exhibited significant anti-tumor activity in NSCLC cells with wild-type EGFR and KRAS." (PMID 38540176, 2024). "LY3537982 has over 10-fold greater potency compared to sotorasib and adagrasib, when considering KRAS GTP loading inhibition, and tumour regression." (PMID 39372214, 2024). "High-level activation of oncogenes (e.g. KRAS, BRAF, and c-MYC) triggers intrinsic tumor suppression." (PMID 38921956, 2024). "Oncogenes and tumor suppressors: Some oncogenes, such as the ones seen in KRAS or MYC, help increase the level of HIF-1α, thereby contributing to tumor development." (PMID 39493156, 2024). "More thorough analyses of SHP2 inhibitor treatment in KRAS- and EGFR-mutant NSCLC models revealed tumor-intrinsic CCL5/CXCL10 secretion." (PMID 38504984, 2024). "Although ZEB1 is best known for triggering an EMT, we found that ZEB1-high in BRAF/Braf-mutant CRCs paradoxically correlated with low tumor budding and a reduced EMT signature, the opposite than in KRAS-mutant CRCs." (PMID 37870961, 2023). "This corroborates data from PDAC models, which have shown that inhibition of downstream KRAS signalling member MEK combined with STAT3 resulted in stromal remodelling and induced anti‐tumour immune responses." (PMID 37199043, 2023). "Also, a recent study indicated that CRC tumor with mutations in the G12 residue of KRAS may not benefit from combining SRC and MEK inhibitors." (PMID 36952536, 2023). "KRAS-mutant LUAD cells express high levels of SLC7A11 and GPX4; pharmacological or genetic inhibition of either SLC7A11 and GPX4 attenuates tumor growth in vivo." (PMID 37161053, 2023). "Further GSEA analysis of tumor hallmarks indicated that oncogenic pathways, including IL6/JAK/STAT3 signaling, KRAS signaling, and Wnt/β‐catenin signaling pathway were engaged in the high‐risk group." (PMID 37334893, 2023). "To investigate the in vivo anti-tumor potency of 1-2C TCR-T cells, we subcutaneously engrafted PANC-1 cells stably expressing the KRAS-G12V mutant gene in a NOD-Prkdcem26Cd52Il2rgem26Cd22/NjuCrl (NCG) mouse model." (PMID 37828002, 2023). "In human KRAS-mutant CRC patients, SLC25A22 expression was positively and negatively correlated with MDSC and CD8+ T-cell tumor infiltration, respectively." (PMID 37542037, 2023). "RT-qPCR of mutant (MUT)-KRAS CRC biopsies and their adjacent normal tissues showed that nearly 67.69% (44/65) of the paired tumor tissues showed the significantly higher expression (T/N > 1.5-fold) of circIFNGR2 (P < 0.05)." (PMID 36639711, 2023). "To specifically probe the potential link between KRAS status and cytotoxic T‐cell tumor infiltrate, we analyzed CD8+ T‐cell density in 76 KRAS mutant CRC tissues and 99 KRAS wild‐type samples." (PMID 36599679, 2023). "The synthesised gold nano-complex suppressed tumour growth for approximately 25 days by controlled delivery of DOX and KRAS-siRNA in Panc-1 cells and subsequent exposing of the nanocomplex with 665 nm light." (PMID 36635659, 2023). "Quadruple editing can significantly inhibit the activation of MAPK and PI3K pathways in KRAS mutant CRC and inhibit tumor growth." (PMID 37020597, 2023).
tumor (continued). "Determining the tumor KRAS status in a patient with stage IV CRC is important, because KRAS-mutant CRC is resistant to EGFR monoclonal antibodies (mAbs) as the mutant RAS continues the activation of the MAPK pathway downstream of EGFR-RAS." (PMID 38139338, 2023). "Especially significant could be the lack of tumor-associated KRAS mutations in PANC02-Luc cells." (PMID 37671865, 2023). "Continuous efforts have been made to target KRAS, HIF1A, and YAP1 because of their roles in tumor initiation." (PMID 37990271, 2023). "In this study, we screened 19 genes associated with ferroptosis, of which 10 FerDEGs such as TLR4, KRAS and HSF1 were highly expressed and 9 FerDEGs such as MUC1, PROM2 and MT1G were lowly expressed in tumour tissue." (PMID 36936437, 2023). "We confirmed tumor regression by TUS-007 administration and moderate KRAS degradation and KRAS signaling suppression in the tumor." (PMID 37513471, 2023). "Our study is limited only to the quantification of cfDNA and should also be analyzed for tumor-specific genomic alterations in cfDNA such as EGFR and KRAS for more precise efficacy prediction and personalized treatment selection." (PMID 37710221, 2023). "The expressions of ITPR2, MDM2, KRAS and CDK4 were also highest in the CLDN2+ AT2 cells, and higher in the tumor-derived CLDN2+ AT2 cells than the normal ones." (PMID 37488117, 2023). "Inflammation promotes tumor formation and accelerates the progression of PanIN to PDAC by inhibiting KRAS-induced senescence." (PMID 37550301, 2023). "It blocks KRAS-MAPK signaling pathway, relieves the immunosuppressive microenvironment of tumors, and enhances the efficacy of existing tumor immunotherapy." (PMID 37669923, 2023). "The inflammation allowed tumor cells to overcome GSK126 antiproliferative effects, an unfavorable event and possibly rendering EZH2 inhibitors ineffective against KRAS-driven NSCLC." (PMID 36986550, 2023). "Concurrent targeting of KRAS and ST8SIA6-AS1/PLK1 signaling suppressed both ERK-dependent and -independent c-Myc expression, synergistically led to cell death and tumor regression and overcame KRASG12Ci resistance." (PMID 38104151, 2023). "Together, these studies identify a promising therapeutic strategy for KRAS-mutant NSCLCs, demonstrate that BCL-2 proteins are the key mediators of the therapeutic response in this tumor type, and uncover a predictive biomarker of sensitivity." (PMID 37384411, 2023). "Among the nine patients with BPM, driver mutations of primary tumours were determined by NGS, including EGFR mutations (5, 55.6%), which include 19del (4, 44.4%), L858R+A871E + MET (1, 11.1%), ALK (1, 11.1%), ROS1 (1, 11.1%), KRAS (1, 11.1%), and unknown (1, 11.1%)." (PMID 38269023, 2023). "This has been attributed to the presence of mutant KRAS oncogene, which has been shown to initiate and upregulate intracellular VEGF expression in a mouse PDAC tumor model." (PMID 37626752, 2023).
tumor (continued). "It promotes tumor cell proliferation, migration, and inflammation; it also indirectly regulates KRAS via targeting NF1, a KRAS inhibitor." (PMID 37371047, 2023). "KRAS codon 2 mutation analysis is not only useful to identify cancer patients with specific KRAS mutations, but also patients with no mutations in that codon, for whom different therapeutic options may be available, namely direct surgery if the tumor is resectable." (PMID 37097304, 2023). "Furthermore, the downstream signaling of KRAS mutation subtypes uniquely alters tumor biology and thus may influence distinct clinical behavior that may not be apparent in examining KRAS mutations in toto." (PMID 37835787, 2023). "This downregulation of miR-665 leads to increased expression of oncogenes like EGFR, BRAF, KRAS, and MYC, which promote tumor cell migration, invasion, and proliferation." (PMID 37894282, 2023). "Encoded by LINC00673, RASON directly binds to KRAS and stabilizes KRAS in its GTP-bound hyperactive state and is therefore required for KRAS-driven tumorigenesis and tumor maintenance." (PMID 36241718, 2023). "In a genetically engineered mouse model of KRAS-driven PDAC, inducible whole-body deletion of xCT led to significant tumor regression." (PMID 36443441, 2023). "The present work also investigated KRAS and CTLA-4 mRNA expression in CTCs and matched primary tumour tissues." (PMID 37761948, 2023). "Tuba-seq analysis of DNA extracted from bulk tumor-bearing lungs allowed us to quantify tumor burden and size across mouse genotypes, and thus determine the tumorigenic potential of BRAF V600E and EGFR L858R relative to KRAS G12C and KRAS G12D." (PMID 37828026, 2023). "This stands in sharp contrast to the dramatic pro-tumorigenic effects observed in the KRAS-driven PDAC model and suggests that SNAIL has context-specific functions in different tumour entities and/or oncogenic backgrounds." (PMID 36882420, 2023). "Transcriptional dysregulation due to alterations in KRAS and MYC affects initiation, development, and survival of this tumor type." (PMID 37831776, 2023). "Conversely, we demonstrate that overexpression of KHKC in KPC cells enhances KRAS downstream pathway, while KHKA overexpression acts as a tumor suppressor by blocking the phosphorylation of ERK1/2 and decreasing RPS6 activation." (PMID 37559908, 2023). "Most recently, KRAS G12D inhibitor MRTX1133 have been shown to inhibit oncogenic KRAS signalling and reduce tumour growth via the inactivation of ERK pathway." (PMID 37790705, 2023). "To test the relevance of our findings in a tumour model, we performed endoscopy-guided injection of 4-OH-tamoxifen in the colonic submucosa of APC and APC KRAS mice." (PMID 37580540, 2023). "MUC1-C suppression was associated with inhibition of epithelial-mesenchymal transition (EMT) and KRAS independence in KRAS mutant NSCLC cells, which contributed to tumor growth inhibition." (PMID 36895477, 2023).
tumor (continued). "We first utilized a PDX model with transplantation of KRAS WT amplification lung tumor in NSG mice to determine the influence of alone or concomitant inhibition of HIF1A-As2 and MYC on tumor growth." (PMID 37041291, 2023). "Targeted data analysis showed that SAM and SAH levels were significantly increased in tumours compared to paired NAT of both APC and APC KRAS mice." (PMID 37580540, 2023). "The results also showed that various tumor types were enriched in TGF-β, protein slicing, oxidative phosphorylation, mTORC1, KRAS, epithelial-mesenchymal transition, and DNA repair signals." (PMID 37600783, 2023). "We first verified ST6GAL1 overexpression in PDAC patient tissues, then established a tumor driver function for ST6GAL1 using tumor xenograft models and GEM models with dual expression of ST6GAL1 and oncogenic KRAS (KRASG12D)." (PMID 37643018, 2023). "The important role of the KRAS signaling and TNF⍺ signaling via NF-κB pathways in tumor progression has garnered significant attention." (PMID 37874419, 2023). "Finally, cancer cell intrinsic and cell extrinsic changes induced by targeted KRAS G12C inhibitors have been recently analyzed in tumor autopsies of a lung cancer patient, providing a real-life picture of the pro-tumorigenic effects of treatment on both tumor cells and the TME." (PMID 36757577, 2023). "Nonetheless, the impact of CRAF on tumorigenesis differs markedly across various KRAS-driven tumor models, and the exact role of CRAF in KRAS-mutant tumors remains to be elucidated." (PMID 38111008, 2023). "Conversely, we recently reported that in hypoxic KRAS mutant tumors, phospholipase C γ1 (PLCγ1) is suppressed, a phenomenon leading to impaired mitochondrial fitness and decreased FAO, which boosts tumor growth." (PMID 36675307, 2023). "Candidate tumor-agnostic molecular targets in the three gynecological malignancies included ERBB2, PIK3CA, ARID1A, and KRAS." (PMID 38201563, 2023). "As a result of the administration of ruxolitinib (a JAK1/2 selective kinase inhibitor) in mouse models, a decline in tumor cell proliferation rate was reported, showing a positive correlation between JAK1/2 and disease progression in KRAS-mutant NSCLC." (PMID 36899885, 2023). "Recent studies indicated that combined inhibition of EGFR and CRAF in KRAS-driven models of PDAC prevented tumor development; therefore, there is a growing interest in targeting CRAF as a strategy to treat KRAS mutant tumors." (PMID 37996408, 2023). "The relationship between KRAS and MYC in tumorigenesis is very complex but BET inhibition in mouse models of KRAS-driven PDAC and NSCLC reduced both tumor size and tumor grade." (PMID 38023987, 2023). "The tumor genome provided us with other therapeutic clues, such as PIK3CA and KRAS, which have corresponding targeted inhibitors." (PMID 36737820, 2023). "Although the structure has not been reported, BI-1701963 was selected as a clinical-stage inhibitor of the SOS1:KRAS PPI, and has displayed tumor regressions in several tumor models in mice when dosed in combination with a KRASG12C inhibitor." (PMID 37108538, 2023). "Patients with higher tumor mRNA levels of both ATR and PrimPol had a lower OS rate than those with KRAS-mutant tumors with lower mRNA levels of both ATR and PrimPol among patients with KRAS-mutant tumors in the LUAD cohort." (PMID 37591859, 2023).